RET (ret proto-oncogene)
Description:
Receptor tyrosine-protein kinase involved in numerous cellular mechanisms including cell proliferation, neuronal navigation, cell migration, and cell differentiation in response to glia cell line-derived growth family factors (GDNF, NRTN, ARTN, PSPN and GDF15). In contrast to most receptor tyrosine kinases, RET requires not only its cognate ligands but also coreceptors, for activation. GDNF ligands (GDNF, NRTN, ARTN, PSPN and GDF15) first bind their corresponding GDNFR coreceptors (GFRA1, GFRA2, GFRA3, GFRA4 and GFRAL, respectively), triggering RET autophosphorylation and activation, leading to activation of downstream signaling pathways, including the MAPK- and AKT-signaling pathways. Acts as a dependence receptor via the GDNF-GFRA1 signaling: in the presence of the ligand GDNF in somatotrophs within pituitary, promotes survival and down regulates growth hormone (GH) production, but triggers apoptosis in absence of GDNF. Required for the molecular mechanisms orchestration during intestine organogenesis via the ARTN-GFRA3 signaling: involved in the development of enteric nervous system and renal organogenesis during embryonic life, and promotes the formation of Peyer's patch-like structures, a major component of the gut-associated lymphoid tissue (By similarity). Mediates, through interaction with GDF15-receptor GFRAL, GDF15-induced cell-signaling in the brainstem which triggers an aversive response, characterized by nausea, vomiting, and/or loss of appetite in response to various stresses. Modulates cell adhesion via its cleavage by caspase in sympathetic neurons and mediates cell migration in an integrin (e.g. ITGB1 and ITGB3)-dependent manner. Also active in the absence of ligand, triggering apoptosis through a mechanism that requires receptor intracellular caspase cleavage. Triggers the differentiation of rapidly adapting (RA) mechanoreceptors. Involved in the development of the neural crest (By similarity). Regulates nociceptor survival and size (By similarity). Phosphorylates PTK2/FAK1. [Isoform 1]: Isoform 1 in complex with GFRAL induces higher activation of MAPK-signaling pathway than isoform 2 in complex with GFRAL.
Synonyms: CDHF12; CDHR16; PTC; RET51; HSCR1; MEN2A; MEN2B; MTC1; RET-ELE1
Tractability: Small molecule: an approved drug acts on it; a structure with a bound ligand is known; a high-quality ligand is known; it has a high-quality binding pocket; it belongs to a druggable protein family. Antibody: UniProt places it where antibodies can reach, with high confidence; its Gene Ontology location is reachable by antibodies, with high confidence; UniProt predicts a signal peptide or a membrane-spanning region. PROTAC: ubiquitination databases record sites on it; a small molecule that binds it is known. Other modalities: a drug acting on it is in phase 2 or 3 trials.
Target class: Protein Kinase; Kinase; Enzyme; Tyrosine protein kinase Ret family; TK protein kinase group
Chemical probes: HG-7-85-01 (high quality), Pralsetinib
Gene: Protein-coding gene on chromosome 10 (43,077,026 to 43,130,351, forward strand). Ensembl gene ENSG00000165731.
Subcellular location: Cell membrane; Endosome membrane
Subcellular location (Human Protein Atlas): Cytosol; Golgi apparatus; Plasma membrane
Pathways (Reactome):
Developmental Biology: Formation of the nephric duct; Formation of the ureteric bud; RET signaling
Gene expression (Transcription): NPAS4 regulates expression of target genes
Signal Transduction: RAF/MAP kinase cascade
Gene Ontology:
Molecular function: calcium ion binding; protein binding; protein tyrosine kinase activity; transmembrane receptor protein tyrosine kinase activity; signaling receptor activity; ATP binding; protein kinase activity
Biological process: cellular response to retinoic acid; GDF15-GFRAL signaling pathway; glial cell-derived neurotrophic factor receptor signaling pathway; membrane protein proteolysis; neuron cell-cell adhesion; positive regulation of cell adhesion mediated by integrin; positive regulation of cell migration; positive regulation of MAPK cascade; positive regulation of neuron projection development; positive regulation of phosphatidylinositol 3-kinase/protein kinase B signal transduction; regulation of cell adhesion; axon guidance; cell surface receptor protein tyrosine kinase signaling pathway; lymphocyte migration into lymphoid organs; Peyer's patch morphogenesis; positive regulation of DNA-templated transcription; positive regulation of extrinsic apoptotic signaling pathway in absence of ligand; positive regulation of metanephric glomerulus development; posterior midgut development; response to pain; signal transduction; homophilic cell-cell adhesion; nervous system development
Cellular component: endosome membrane; plasma membrane; plasma membrane protein complex; receptor complex; axon; membrane
Genetic constraint (gnomAD): Loss-of-function variants: 19 observed, 116.16 expected, observed/expected ratio (o/e) 0.16, 90% interval 0.11 to 0.24. The upper end of that interval is the gene's LOEUF score, 0.24, which puts it in group 1 of 6, group 1 being the genes least tolerant of losing a copy. Missense variants: 1,210 observed, 1,495.2 expected, observed/expected ratio (o/e) 0.81, 90% interval 0.77 to 0.85. Synonymous variants: 590 observed, 642.21 expected, observed/expected ratio (o/e) 0.92, 90% interval 0.86 to 0.98.
Gene-disease validity (ClinGen):
ClinGen rates the evidence that RET causes each of these diseases.
multiple endocrine neoplasia type 2A (autosomal dominant): Definitive. An autosomal dominant tumor predisposition disorder caused by pathogenic variants in the RET gene, characterized by an increased risk of medullary thyroid carcinoma, pheochromocytoma, and hyperparathyroidism.
multiple endocrine neoplasia type 2B (autosomal dominant): Definitive.
Cancer hallmarks: tumour promoting inflammation (promotes); escaping programmed cell death (suppresses); proliferative signalling (promotes); escaping programmed cell death (promotes); escaping immune response to cancer (promotes); invasion and metastasis (promotes)
Homologues: Orthologues: macaque RET (98% identical), chimpanzee RET (97% identical), rabbit RET (89% identical), pig RET (87% identical), rat Ret (85% identical), dog RET (84% identical), mouse Ret (83% identical), guinea pig RET (80% identical), zebrafish ret (59% identical), Drosophila melanogaster Ret (24% identical), tropical clawed frog flt1 (8% identical). Paralogues in human: MET (19% identical), MST1R (19% identical), ROS1 (18% identical), FGFR2 (17% identical), FLT1 (17% identical), FLT4 (16% identical), FGFR3 (16% identical), KIT (16% identical), FGFR1 (16% identical), IGF1R (16% identical), KDR (16% identical), FGFR4 (16% identical), and 41 more.
Diseases named in the same sentence as RET in open-access papers:
RET is named in the same sentence as 479 diseases in open-access papers, as found by Europe PMC text mining. Sharing a sentence is not in itself a finding about the gene and the disease. The quoted sentences say what the papers report.
thyroid cancer (470 papers, 1993 to 2026). "In the NCT03037385 clinical trial, pralsetinib achieved an ORR of 71% in patients with RET-mutated MTC and an ORR of 89% in patients with RET fusion-positive thyroid cancer." (PMID 41278287, 2025). "An anti-RET drug such as selpercatinib is approved for the treatment of patients with RET mutations in thyroid cancer and non-small cell lung cancer with RET fusion." (PMID 40129918, 2025). "The central oncogenic role of RET in thyroid cancer, its association with unfavorable prognosis, and the limitations of multi-kinase inhibitor therapy collectively establish a powerful rationale for drug development." (PMID 41278287, 2025). "This approach has already facilitated the development of targeted therapies, such as inhibitors for BRAF and RET mutations, which are commonly implicated in thyroid cancer." (PMID 40297138, 2025). "In the phase 1/2 LIBRETTO-001 trial, the selective RET inhibitor selpercatinib demonstrated a favorable response rate and improved progression-free survival (PFS) in RET mutation-positive MTC or fusion-positive thyroid cancers." (PMID 40638225, 2025). "Regarding tyrosine kinase inhibitors, a phase 1-2 clinical trial 154 evaluated selpercatinib in patients with medullary thyroid cancer with a RET mutation and patients with RET fusions thyroid cancer." (PMID 39744583, 2025). "The RET proto-oncogene serves as a key driver in the development of thyroid cancer, and its alterations are closely associated with highly aggressive tumor subtypes." (PMID 41278287, 2025). "A comprehensive analysis of the molecular mechanisms underlying thyroid cancer revealed that the RET proto-oncogene is a central driver of its development." (PMID 41278287, 2025). "A noteworthy finding is that endogenous-ADAR can address all SNVs within the RET gene associated with thyroid cancer." (PMID 40330550, 2025). "Due to its involvement in the embryogenesis of several body systems, RET fusions and mutations are found in a diverse set of cancers including lung, colorectal, breast, and thyroid cancers." (PMID 41179283, 2025). "RET mutation and RET fusion/rearrangements are more likely to occur in thyroid cancer than in lung cancer." (PMID 38705930, 2024). "Selpercatinib is approved by US FDA for the treatment of thyroid cancer with RET gene mutations or fusions." (PMID 39473507, 2024). "Selective rearranged during transfection (RET) tyrosine kinase inhibitor, pralsetinib, demonstrated clinical efficacy and was well tolerated in lung and thyroid cancers with RET gene mutations or fusions in clinical trials." (PMID 39139787, 2024). "For example, BRAF V600E and RAS mutations are the main genetic drivers in thyroid cancers, followed by fusions involving RET and other receptor tyrosine kinases." (PMID 38504322, 2024). "RET mutations have been identified in several cancer types, with thyroid cancer and lung cancer having the highest prevalence." (PMID 38738791, 2024). "Selective RET tyrosine kinase inhibitors demonstrated striking clinical efficacy in lung and thyroid cancers with RET gene mutations or fusion with an overall response rate as high as 70% among treatment-naive patients." (PMID 39139787, 2024). "Initially discovered during a human proto-oncogene screen, the RET gene is commonly implicated in thyroid cancers, congenital megacolon, and non-small-cell lung cancers." (PMID 38397034, 2024). "We demonstrate that a combination of selpercatinib and MitoQ can effectively and synergistically suppress RET-mutated thyroid cancers." (PMID 38378752, 2024).
thyroid cancer (continued). "At present, studies have shown that mutations, including fusions, involving the BRAF and RET genes are associated with a higher likelihood of a clinical diagnosis of thyroid cancer." (PMID 39558959, 2024). "The highly selective RET inhibitors (e.g. selpercatinib and pralsetinib) have led to a paradigm change in the treatment of RET-mutated thyroid cancers, thanks to their strong efficacy and tolerable toxicity profile." (PMID 39136571, 2024). "A recent meta-analysis showed strong epidemiological evidence of associations through the Venice criteria and false-positive report probability between thyroid cancer susceptibility and RET rs1799939." (PMID 37189693, 2023). "As FDA approves larotrectinib and entrectinib for solid tumors with NTRK gene fusions, and pralsetinib and selpercatinib for thyroid cancers with RET gene mutations or fusions." (PMID 37124750, 2023). "Thyroid cancer is another tumor type with a high mutation positivity rate of 74% with BRAF at 40% followed by RET at 17.3%." (PMID 37483495, 2023). "New and highly selective drugs, such as LOXO-292, show potential for the treatment of thyroid cancer with RET gene mutations Our second case was a collision cancer of FTC combined with PTC." (PMID 37580706, 2023). "RET fusion genes have been studied in association with exposure to ionizing radiation during childhood and the development of thyroid cancer." (PMID 37882481, 2023). "Changes in the RET gene (like mutations or fusions) are often found in lung and thyroid cancers but are also found in other cancer types." (PMID 37627175, 2023). "For instance, in the case of a 53‐year‐old male thyroid cancer patient, we discovered that the tumor diameter exceeds 1 cm and presents a RET mutation." (PMID 37081757, 2023). "In 2021, pralsetinib was approved by the FDA to treat lung and thyroid cancers with mutations or fusions of the RET gene." (PMID 38248091, 2023). "RET proto-oncogene was identified more than 30 years ago, and the rearrangement and mutation of RET have been reported in a variety of cancers, including thyroid cancer, non-small cell lung cancer, and breast cancer." (PMID 36865807, 2023). "Of note, additional thyroid cancer subtypes can also be associated with RET fusions although at a lower prevalence, including poorly differentiated thyroid carcinoma (5%) and anaplastic thyroid cancer (1%)." (PMID 37627175, 2023). "Thyroid cancer is associated with a broad range of different mutations, including RET (rearranged during transfection) fusion genes." (PMID 37882481, 2023). "Several preclinical trials used PDXMs to evaluate targeted therapy for thyroid cancer, including vemurafenib for PTC, the selective RET kinase inhibitor LOXO-292 for RET-mutated thyroid cancer, PLX51107 and PD0325901 for ATC, and cabozantinib for MTC." (PMID 37446316, 2023). "In another phase 1–2 study, pralsetinib was tested in patients affected by RET-mutated thyroid cancer (both with MTC or with RET fusion–positive thyroid cancer)." (PMID 36139603, 2022). "Selpercatinib and pralsetinib, tyrosine-kinase inhibitors with a high specificity for RET protein, recently obtained FDA approval for the treatment of Lung and Thyroid Cancers with RET gene mutations or fusions." (PMID 36053791, 2022). "Selpercatinib is now established as one of two first-in-class FDA approved selective RET inhibitors for lung and thyroid cancers with RET mutations or fusions." (PMID 35304457, 2022). "Recently two new selective RET inhibitors, selpercatinib and pralsetinib, have shown significant efficacy in treating patients with RET gene rearrangements and activating mutations, in both lung and thyroid cancers." (PMID 35510953, 2022). "In Thyroid cancer we found a variant in RET which has previously been linked to worse survival for patients." (PMID 36497297, 2022).
thyroid cancer (continued). "In cancer cases, all colon cancer cases were affected by pathogenic variants in MLH1 and SBDS genes, while 20% (2/10) of the thyroid cancer cases by RET c.1900T>C variants were affected." (PMID 36428697, 2022). "Mutations in the TERT promoter have been identified in thyroid cancer, including in RET-rearranged thyroid cancer, but their association with disease progression has been unclear." (PMID 35510953, 2022). "Collectively, our work provides new potential precision medicine approaches for cancer patients with upregulated hTERT expression, perhaps, especially those harboring mutations in both the RET gene and the hTERT promoter, such as in thyroid cancer." (PMID 36142729, 2022). "RET-rearranged thyroid cancer has been associated with exposure to radiation, younger age of onset, a tendency to concentrate radioactive iodine, and in some patients, an indolent clinical course." (PMID 35510953, 2022). "BRAF mutations are the most common genetic alterations in thyroid cancer (59.7%), while RET fusions are present in about 10%–20% of differentiated thyroid cancer." (PMID 36091770, 2022). "Predictive markers for single entities (BRAF V600E, RET mutations and RET fusions) should be tested in all advanced thyroid carcinomas." (PMID 35013772, 2022). "RET mutations and fusions have been documented in pediatric thyroid cancer and are associated with a more aggressive phenotype via downstream signaling through MAPK, PI3K, and JAK-STAT." (PMID 34298746, 2021). "There has unquestionably been a substantial dose-dependent excess risk of Iodine-131 related radiogenic thyroid cancer, many with a distinctive histopathology RET/PTC3." (PMID 34069605, 2021). "More specific kinase inhibitors target driver mutations, e.g., selpercatinib, in RET-mutated thyroid cancers." (PMID 34298656, 2021). "Apart from clinicopathological characteristics, several genic features (such as BRAF, TERT, and RET) can be applied for risk stratification and prognostic scoring systems of thyroid cancer patients." (PMID 35433709, 2021). "Although initially believed to be pathogenic for thyroid cancer, these mutations were recently demonstrated to have a pathogenic effect only if co-occurring with other RET mutations." (PMID 33670055, 2021). "A lot of research has been conducted on mutated constitutively active forms of RET, which play a major role in thyroid cancer, pheochromocytoma, and parathyroid hyperplasia, as well as in the development of lung cancer in a subset of patients." (PMID 32993133, 2020). "RET was first identified 35 years ago, and its oncogenic rearrangements and mutations have been reported in a variety of cancers, including thyroid cancer, NSCLC, MEN2A, and MEN2B." (PMID 33150251, 2020). "Most thyroid cancers are closely related to MAPK, VEGF, and PI3K signaling pathways, while BRAF, RAS and RET genes have higher mutation rates, which provides molecular targets for thyroid cancer." (PMID 33519470, 2020). "In vitro irradiation with -rays generated KIF5B-RET fusion in lung cells, thus pointing, similar to thyroid cancer, to radiation as a possible risk factor for RET fusion in lung cancer." (PMID 32326537, 2020). "The most typical oncogenic drivers of MTC, a thyroid carcinoma arising from C-cells, are RET point mutations, both in sporadic and familial cases." (PMID 32326537, 2020). "Vandetanib is used for the treatment of symptomatic or progressive medullary thyroid cancer, probably because the RET tyrosine kinase mutation occurs in this type of thyroid cancer." (PMID 31295928, 2019). "Activating mutations of the RET gene have been described for both papillary (chromosomal rearrangement) and medullary (missense mutations) thyroid carcinomas." (PMID 31921336, 2019).